CDK4 (cyclin dependent kinase 4)
Diseases named in the same sentence as CDK4 in open-access papers (continued):
Sharing a sentence is not in itself a finding about the gene and the disease.
chronic myeloid leukemia (5 papers, 2009 to 2023). "KEGG analysis in the BaF3-T315 cells showed that the chronic myeloid leukemia signaling pathway (genes such as Cdk4, Tgfbr1, Gadd45b, Mdm2, Gadd45g, Polk, Rb1, Ctbp1, and Cdkn2a were enriched) was involved in the I13 treatment." (PMID 37124196, 2023). "Western blot results confirmed that UNC13B may modulate the apoptosis and proliferation of arsenic trioxide-resistant chronic myeloid leukemia cells through the mediation of MAP3K7, CDK4, and PINK1." (PMID 35707364, 2022). "One can speculate that potentially CDK4/6 is mutated in these cell lines and does not allow PD 0332991 binding and kinase inhibition, as is the case in resistance to BCR-ABL inhibitors in chronic myelogenous leukemia." (PMID 19874578, 2009).
Cirrhosis (5 papers, 2012 to 2025). A chronic disorder of the liver in which liver tissue becomes scarred and is partially replaced by regenerative nodules and fibrotic tissue resulting in loss of liver function. "Similarly, when β was calculated when tumor size, BCLC stage and cirrhosis as adjusted factors, risk score = expression of CDK1 × 0.792 + expression of CDK4 × 0.024 in GSE14520 cohort." (PMID 35193513, 2022).
colon adenocarcinoma (5 papers, 2018 to 2022). "Known Hsp90 clients EGFR, HER2, CDK4, CDK6, CXCR4, Akt-1, c-Raf, Survivin, ERK-5 and Integrin α2 were analyzed following the administration of KUNB31 to HT29 (colon adenocarcinoma grade II) cells." (PMID 29382832, 2018).
dedifferentiated liposarcoma (5 papers, 2017 to 2025). A high-grade subtype of liposarcoma (LS) that progresses from well-differentiated liposarcoma (WDLS), and most often occurs in the retroperitoneum. "Dedifferentiated liposarcoma (DDLPS) also often has amplifications of the MDM2 and CDK4 genes." (PMID 41123840, 2025).
diffuse large B-cell lymphoma (5 papers, 2013 to 2025). "A study previously demonstrated that mepacrine induced G0/G1 cell cycle arrest and apoptosis in diffuse large B‐cell lymphoma cell lines in a dose‐dependent manner and downregulate MYC cyclin‐dependent kinase 4/6 expression." (PMID 41025936, 2025).
ependymoma (5 papers, 2015 to 2025). A WHO grade II, slow growing tumor of children and young adults, usually located intraventricularly. "By analyzing differential gene expression signatures between normal and tumor public ependymoma microarray datasets, we identified that most of the cell-cycle-associated genes are upregulated, and CDK4/6-cyclin D1 complexes are the major upstream regulators in the cell cycle process." (PMID 33271970, 2020). "Abemaciclib is a CDK4/6 inhibitor that was shown to inhibit the growth of an ependymoma in our previous study." (PMID 37046450, 2023). "The CDK4/6 inhibitor abemaciclib showed promising therapeutic effects in primary ependymoma cells and in a preclinical ependymoma animal model and, thus, represents a potential therapeutic strategy." (PMID 33271970, 2020). "By using integrated bioinformatics and through experimental validation, we found that at least one of the genes CCND1 and CDK4 is overexpressed in ependymomas." (PMID 33271970, 2020). "In support of the strategy of targeting the CDK4/6–cyclin D1 complex for more effective treatment of ependymomas, a study demonstrated that abemaciclib, compared to other CDK4/6 inhibitors, has a higher efficiency in passively crossing the BBB." (PMID 33271970, 2020). "The array hybridization intensity showed that CDK4 and CCND1 are significantly upregulated in supratentorial and posterior fossa ependymomas." (PMID 33271970, 2020). "CDK4, CCND1, and RB1 were found to be upstream regulators in the cell cycle process; therefore, CDK4 and CCND1 seem to be the main targets in ependymomas." (PMID 33271970, 2020). "In this study, integrated transcriptome analysis demonstrated that the cell cycle-related genes CDK4 and CCND1 are upregulated in ependymomas." (PMID 33271970, 2020). "Nonetheless, the role of protein kinase signaling has been implied in ependymoma tumorigenesis, prompting several ongoing studies evaluating TKIs targeting RET, ALK, ROS, IGFR, PDGFR, FGFR, or EGFR, as well as inhibitors targeting PI3K, mTOR, KIT, and CDK4." (PMID 40238025, 2025). "To verify whether CDK4 and CCND1 are overexpressed in ependymomas, we first checked the expression levels of CCND1 and CDK4 in the microarray dataset." (PMID 33271970, 2020). "However, our combined approach identified novel potential biomarker candidates in ependymoma with a known relationship to cancer: ERRB2, EGFR, TWIST1, CDK4, HDAC9, and ARHGEF5 genes." (PMID 26185765, 2015).
intimal sarcoma (5 papers, 2023 to 2025). A malignant neoplasm arising from the large blood vessels. "Similarly, intimal sarcomas exhibit a much higher frequency of MDM2/CDK4 amplification, which serves as a valuable diagnostic tool for pathologists." (PMID 38275873, 2024). "Additionally, it is known that not only MDM2 gene amplification but also CDK4 and PDGFR gene amplification can occur together in intimal sarcoma." (PMID 37395142, 2023).
lobular breast carcinoma (5 papers, 2011 to 2025). "Trials combining checkpoint inhibitors with CDK4/6i or ET have yielded mixed results, but certain histologies, such as lobular carcinoma, may harbor enhanced sensitivity." (PMID 40989687, 2025). "It is not clear if patients with lobular breast carcinomas (LBC) derive the same benefits when receiving second line CDK4/6i." (PMID 33353132, 2020).
myxoid liposarcoma (5 papers, 2017 to 2025). A liposarcoma characterized by the presence of round non-lipogenic primitive mesenchymal cells and small signet ring lipoblasts within a myxoid stoma with a branching vascular pattern. "Immunohistochemistry results were also conflicting; although CD34(−) and CDK4(−) matched typical myxoid liposarcoma characteristics, the negative S-100 staining differed from the usual S-100 positivity seen in myxoid liposarcoma, further complicating accurate identification." (PMID 41143184, 2025). "At RNA sequencing, significantly elevated expression, compared to myxoid liposarcomas, was seen for TRIO and AMACR in 5p and of CDK4, HMGA2 and MDM2 in 12q." (PMID 28652867, 2017). "Of the selected target genes, AMACR and TRIO in 5p and CDK4, HMGA2 and MDM2 in 12q showed significantly (p < 0.05) elevated expression in relation to myxoid liposarcomas." (PMID 28652867, 2017).
neuroendocrine tumors (5 papers, 2020 to 2024). "Recently, we demonstrated the CDK4/6 inhibitor ribociclib (LE011) to exhibit significant antitumoral activity in human neuroendocrine tumor cell lines in vitro." (PMID 33807122, 2021). "Further preclinical in vivo studies and clinical studies should investigate the therapeutic efficacy of MEK inhibitors alone and in combination with CDK4/6 inhibitors in neuroendocrine neoplasms." (PMID 33807122, 2021). "In neuroendocrine tumors, the CDK4/6 inhibitor palbociclib (PD-0332991) demonstrated significant antitumoral activity in a preclinical in vitro and in vivo model." (PMID 33807122, 2021). "In this study we investigated the effects of the MEK inhibitor trametinib, the ERK inhibitor SCH772984 and the CDK4/6 inhibitor ribociclib in human neuroendocrine tumor cell lines BON1, QGP1 and NCI-H727 in vitro." (PMID 33807122, 2021). "Combination therapy of MEK inhibitors and CDK4/6 inhibitors might be a potential strategy to overcome CDK4/6 inhibitor resistance in neuroendocrine tumors." (PMID 33807122, 2021). "Transfection of neuroendocrine tumor cell lines with the product of MIR1-2, MIR1-3p, decreased expression of CDK4, decreased phosphorylation of RB, prevented cell growth and caused cell cycle arrest." (PMID 32198354, 2020). "Future investigations in patient-derived primary tumor cultures, spheroids, and organoids should also focus on somatic mutations or signaling cascade alterations to characterize predictive biomarkers in neuroendocrine tumors for the therapeutic response to dual MEK inhibition and CDK4/6 inhibition." (PMID 33807122, 2021).
psoriasis (5 papers, 2008 to 2025). An autoimmune condition characterized by red, well-delineated plaques with silvery scales that are usually on the extensor surfaces and scalp. "Similarly, cyclin D1, CDK2, and CDK4 expression is increased in psoriatic lesions of psoriasis patients." (PMID 34639115, 2021).
serous carcinoma (5 papers, 2016 to 2024). "RB1 loss was a characteristic of high-grade serous carcinomas, and potentially limited postulated CDK4/6 actionability in some high-grade serous carcinoma patients." (PMID 33947352, 2021). "Postulated sensitivity to CDK4/6 inhibitor therapy was mostly due to CCND1 gain – particularly in patients with high-grade serous carcinomas- and CDKN2A loss." (PMID 33947352, 2021). "Block expression of p16 in clear cell and endometrioid carcinoma should be further validated as a prognostic marker, and absence in low‐grade serous carcinoma justifies CDK4 inhibition." (PMID 30062862, 2018).
solitary fibrous tumor (5 papers, 2024 to 2025). Solitary fibrous tumor (SFT) represents a diverse group of ubiquitous rare spindle cell neoplasms that may be benign or malignant and that most frequently arises from the pleura and peritoneum and rarely from other sites such as head and neck, liver and skeletal muscle. "The absence of STAT6 and H3 K27Me3 loss excludes solitary fibrous tumor (SFT), and the lack of p16 and CDK4 rules out dermatofibrosarcoma protuberans (DFSP)." (PMID 40556675, 2025). "Negative staining for MDM2 and CDK4, CD34 and STAT6, and c-kit and DOG1 led to the exclusion of dedifferentiated liposarcoma, solitary fibrous tumor (SFT), and GIST, respectively." (PMID 38739347, 2024).
type 2 diabetes (5 papers, 2013 to 2023). "β cell failure in the IRS2-deletion mouse type 2 diabetes model is, in part, due to loss of CDK4 regulator cyclin D2." (PMID 37712417, 2023). "Specifically, the type 2 diabetes-associated cyclin-dependent kinase inhibitor 2A, which strongly inhibits the proliferative cyclin-dependent kinase 4 (CDK4), was enriched in PAX4R129W islets whereas it was decreased in PAX4 islets." (PMID 26813254, 2016). "In human skeletal muscle, we observed that markers of oxidative fibers and mitochondria correlated positively with expression levels of PPARGC1A and CDK4 and negatively with expression levels of CDKN2A, a locus significantly associated with type 2 diabetes." (PMID 37395281, 2023).
acute lymphoblastic leukemia (4 papers, 2019 to 2024). Leukemia with an acute onset, characterized by the presence of lymphoblasts in the bone marrow and the peripheral blood. "Rb is not phosphorylated on Ser608 residue and is tethered to nuclear structures in CD34+ hemopoietic progenitor cells, suggesting that it has growth-suppressive activity, whereas Rb(Ser608) is phosphorylated by CDK4/6 complexes in acute lymphoblastic leukemia cells." (PMID 31784636, 2019).
angiosarcoma (4 papers, 2021 to 2025). A malignant tumor arising from the endothelial cells of the blood vessels. "Specifically, in mice older than 28 weeks containing various combinations of global Cdkn1a/Cdkn1b deletion in addition to a Cdk4 mutation (i.e., hetero- or homozygous deletion/mutation), between 9 and 56% of all spontaneously formed tumors were angiosarcomas." (PMID 33078209, 2021). "A recent study analyzed tumors from animals overexpressing mutated Cdk4 or Cdk6, which severely impairs the function of all four Cdkn2 cell cycle regulators but not of p19ARF, and found that 56% of all tumors in these animals were angiosarcomas." (PMID 33078209, 2021).
atypical lipomatous tumor (4 papers, 2014 to 2025). An intermediate, locally aggressive lipomatous neoplasm. "Well-differentiated liposarcoma (WDL) or atypical lipomatous tumor (ALT) can mimic ASPLT but are characterized by MDM2 and CDK4 positivity, markers that are absent in ASPLT." (PMID 41527615, 2025).
Burkitt lymphoma (4 papers, 2012 to 2022). A rare form of malignant mature B-cell non-Hodgkin lymphoma. "In summary, CDK4/6 inhibitors are shown here to inhibit proliferation of PEL, KSHV-infected endothelial cells, and EBV+ Burkitt’s lymphoma cells and also to reverse virus-induced suppression of MHC-I, ICAM-1, and B7-2 on these cells." (PMID 35562811, 2022). "Three CDK4/6 inhibitors, abemaciclib, palbociclib, and ribociclib, inhibited cell growth in KSHV-induced primary effusion lymphoma (PEL) and EBV positive Burkitt’s lymphoma (BL) cell lines, and KSHV-infected human umbilical vein endothelial cells (HUVECs)." (PMID 35562811, 2022). "However, MYC is not the only HSP90 client protein in Burkitt lymphoma, and so it is possible that the mechanism of action is not exclusively through MYC, but involves the destabilization of cell cycle regulators such as CDK2 and CDK4 directly due to loss of HSP90 function." (PMID 30453475, 2018).
carcinoids (4 papers, 2009 to 2025). "Based on our results, carcinoids seem to use the signaling cascade via upregulation of CDK4/6 and CCND1 expression to control RB1 phosphorylation." (PMID 26008974, 2015). "Carcinoids have increased CDK4/6 and CCND1 expression controlling RB1 phosphorylation via this signaling cascade." (PMID 26008974, 2015). "In addition, IFN-α inhibited cyclin dependent kinases (CDK), CDK2-, CDK3-, CDK4-, and cyclin E- but not cyclin A-associated kinase activities and induced cell cycle arrest in carcinoid tumor." (PMID 26993600, 2016). "Conversely, amplifications of these genes were seen only rarely in conventional SCLC and carcinoids; for example, CDK4 amplifications were found in 0% of SCLC (P = 0.0006) and 1% of carcinoids (P = 0.01)." (PMID 39185963, 2025). "A study on Bon-1 carcinoid cells showed that PDCD4 not only suppressed the transcription of the mitosis-promoting factor cyclin-dependent kinase 1(CDK1)/cdc2, but also decreased the expression of CDK4/6." (PMID 19480673, 2009). "Additionally, CDKN2A, the regulatory inhibitor of CDK4/6, shows minimal to no expression in carcinoids." (PMID 26008974, 2015).
colitis (4 papers, 2017 to 2024). Inflammation of the colon. "We observed that DSS increases the expression of STAT3-related proteins, i.e. Cdk4 and cyclin D1, whereas RA inhibits these increases in the colons of mice with DSS-induced colitis." (PMID 28383063, 2017). "However, aside from these markers, there were no noteworthy disparities in the expression levels of liver regeneration markers, such as Cyclin D, cdk2, cdk4, and eNOS, between DSS-exposed colitis mice and those subjected to ZPE treatment." (PMID 39458516, 2024).
gastrointestinal stromal tumor (4 papers, 2018 to 2025). "Additionally, studies on gastrointestinal stromal tumor (GIST) cell lines with intact RB revealed that the dual inhibition of CDK2 (PF-06873600, CDK2 inhibitor II) and CDK4/6 (palbociclib or abemaciclib) effectively arrested cells in the G1 phase." (PMID 40282469, 2025).
Hyperglycemia (4 papers, 2020 to 2022). An increased concentration of glucose in the blood. "In addition, hyperglycemia is reported in nearly all kinds of PI3K/AKT/mTOR inhibitors but only in two CDK4/6 inhibitors (palbociclib and dalpiciclib)." (PMID 36091147, 2022). "As for common safety concerns, CDK4/6 inhibitors and PI3K/AKT/mTOR inhibitors showed different profiles in hepatotoxicity, gastrointestinal (GI) toxicity, and hyperglycemia." (PMID 36091147, 2022).
insulinomas (4 papers, 2016 to 2019). "Studies in mice with constitutive activation of Cdk4 showed hyperplasia in their pancreatic islets resembling insulinomas." (PMID 29853883, 2018). "Differential expression of UCH-L1, MAP1B, MAP2, VCAN, CDK4 and PDX-1 was verified in more than 40 PNETs, including insulinomas and non-insulinomas by IHC but the expression of CaSR was only validated in 29 insulinomas." (PMID 28526880, 2017).
Luminal breast cancer (4 papers, 2019 to 2025). "Luminal breast cancer commonly exhibits cyclin D1 and CDK4 amplification, while endocrine therapy-resistant tumors often exhibit deregulation of the CDK4/6 pathway." (PMID 31878959, 2019).
lymphopenia (4 papers, 2022 to 2023). Reduction in the number of lymphocytes. "Although the results are not significant probably due to the lack of power, our study provided further evidence that lymphopenia is a negative prognostic factor for PFS and OS for patients receiving CdK4/6i." (PMID 36741710, 2022).
malignant peripheral nerve sheath tumor (4 papers, 2019 to 2025). Malignant peripheral nerve sheath tumor (MPNST) is a rare and often aggressive soft tissue sarcoma occurring in a wide range of anatomical sites. "In hepatocellular carcinoma, even malignant peripheral nerve sheath tumors (MPNSTs), CDK4/6is cause tumors to be more sensitive to PD-L1 blockade therapy by increasing the expression of PD-L1." (PMID 41463246, 2025). "Malignant peripheral nerve sheath tumors (MPNSTs) exhibit a significant increase in B cell/plasma cell infiltration along with tumor shrinkage after CDK4/6-MEK inhibition." (PMID 41463246, 2025).
mesenchymal neoplasm (4 papers, 2015 to 2026). "MDM2 and CDK4 overexpression are not usually seen in benign tumors but quite common in intermediate or malignant mesenchymal tumors and was diffusely positive in this case." (PMID 26315812, 2015).
neuroendocrine carcinoma (4 papers, 2021 to 2024). A malignant neuroendocrine neoplasm composed of cells containing secretory granules that stain positive for NSE and chromogranin. "HER2 and CDK4 regions were analyzed in both adenocarcinoma and neuroendocrine carcinoma components of Ov-MiNEN and neither HER2 nor CDK4 amplification was observed, albeit polysomies of chromosomes 12 and 17 were found." (PMID 34342838, 2022).
pituitary adenoma (4 papers, 2014 to 2022). "The relevance of INK4 family proteins in pituitary adenoma formation is further supported by the analysis of knock-in mice, which express a CDK4 variant with a mutation that renders the Cdk4 protein insensitive to INK4 inhibitors (Cdk4R24C/R24C mutant mice)." (PMID 25136513, 2014). "Importantly, the knockdown of β-Catenin inhibited pituitary adenoma cell proliferation and migration probably by inhibiting AKT, STAT3, Cyclin D1, CDK4, MMP-2, and MMP-9." (PMID 35928898, 2022).
prostate tumor (4 papers, 2016 to 2025). "Additionally, we observed significantly reduced mRNA expression levels of CCND1, p15INK4b, and RB in prostate tumor tissues compared to BPH tissues, while the expression levels of CDK4, CDK6, and p16INK4a remained unaltered." (PMID 40304827, 2025).